IGF1R (insulin like growth factor 1 receptor)
Diseases named in the same sentence as IGF1R in open-access papers (continued):
Sharing a sentence is not in itself a finding about the gene and the disease.
tumor (continued). "Taken together, these data suggest the function of IGF-1R is dependent on the tumor type and signaling context." (PMID 30458886, 2018). "Following the failure of the IGF-targeting strategies, another possible approach is identifying predictive tumor biomarkers that will increase the efficacy of IGF1R-targeted therapy." (PMID 29922232, 2018). "The excessive expression in tumors and their role in tumor development makes IGF-1R is an auspicious bio molecular target for cancer treatment." (PMID 29861465, 2018). "Here, we report that miR-130a and miR-145 are down-regulated in myeloid cells from tumor-bearing mice leading to increased TβRII, as well as multiple mediators in IGF1R signaling pathways." (PMID 29973593, 2018). "Particularly, we were able to detect unique activation of EGFR and IGF1R in CAF cells due to the communication with tumor cells." (PMID 29946230, 2018). "Tumor-specific IGF1R levels have later been evaluated in this cohort and tumor IGF1Rstrong protein expression conferred a worse prognosis than weaker expression." (PMID 29928262, 2018). "Herein, we report a case of malignant SFT associated with a hypoglycemia attack, and we discuss the associations among IGF2, IGF1R, and IGF2R in SFT based on analyses of the tumor in this case." (PMID 30168002, 2018). "The insulin like growth factor 1 (IGF-1) and its receptor (IGF-1R) facilitate tumor proliferation and progression." (PMID 30213025, 2018). "After 40 days of treatment, the tumor volume for IGF-1R siRNA was found approximately 200 mm3, whereas for the control group it was approximately 490 mm3." (PMID 29861465, 2018). "Collectively, these diverse results support the possibility that the IGF-1R has a dual function as both a tumor suppressor and an oncogene." (PMID 30458886, 2018). "Historically, IGF-1R was proposed to have oncogenic effects in breast tumorigenesis, where overexpression or hyperactivation leads to increased tumor cell proliferation and survival." (PMID 30458886, 2018). "SST itself attenuates Insulin Growth Factor 1 (IGF-1) signaling and IGF-1 Receptor (IGF-1R) is important in GEP-NET tumor growth factor biology." (PMID 29973528, 2018). "The anti-sense siRNA targeting IGF-1R along with PEI reduced 60% of tumor volume and increased apoptotic cell expression more than 60% in lung adenocarcinoma." (PMID 29861465, 2018). "One mechanism of tumor suppression is the direct regulation of IGF1R by miR-376a and miR-376c, resulting in decreased migration and proliferation." (PMID 30042829, 2018). "In tumor lesions, the local expression of CCL5 was negatively associated with the expression of the IGF1R (r =-0.6614, p< 0.0001)." (PMID 29156819, 2017). "Using fluorescence in situ hybridization (FISH), which allows sensitive and specific examination of individual tumour cells, we found high-level amplification of IGF1R, defined as 15 copies or more, in 12/87 (14%) cases." (PMID 28643781, 2017). "Previous experimental studies have shown activation of host immune response to tumor cells after IGF-1R knock-down using anti-sense based strategies." (PMID 28447314, 2017). "Many studies in various cell lines and animal tumor models have demonstrated that PPP inhibits IGF-1R activity or its downstream signaling pathways." (PMID 29113409, 2017). "As a consequence of these changes in rRNA methylation, the translation of messages with IRESs is increased; such as those with products that promote tumor development (IGF-1R, c-myc, VEGF-A and FGF1)." (PMID 28808137, 2017). "A number of studies have investigated the effect of IGF1R and IR inhibitors on ERα+ tumor cell proliferation and growth." (PMID 29099049, 2017). "In this study, to gain more insight in to the modulation of tumor development and progression by chronic IGF1R activation, we used a systematic in-depth next-generation sequencing (NGS) approach." (PMID 28173837, 2017).
tumor (continued). "Up-regulating miR-497 in HepG2 and Hep3B cell lines and xenograft models resulted in the down-regulation of IGF1R and mTOR and inhibition of tumor growth and cell invasion." (PMID 28624790, 2017). "This is common for other IGF1R-positive tumour cells where PPP induced apoptosis and reduced cell survival, with IC50 values in the range of 0.05–0.5 μM." (PMID 28793874, 2017). "Taken together, our results suggest that miR-497 and/or miR-99a can work as tumor suppressor in combination synergistically inhibit tumor growth via co-targeting IGF1R and mTOR." (PMID 28624790, 2017). "Both the EGFR and IGF-1R contributed to tumor development and progression through their effects on cell proliferation, apoptosis and angiogenesis, and both were overexpressed in NSCLC cells." (PMID 28460483, 2017). "As a result, the IGF1R has been studied as a target for the development of tumor-specific gene therapy." (PMID 27486969, 2017). "IGF1R, a well‐known cancer drug target, is a transmembrane receptor with tyrosine kinase activity and plays a crucial role in malignant transformation and tumor cell proliferation and survival." (PMID 27891760, 2017). "Tumor promoting activity of insulin can be mediated by insulin receptor (INSR) as well as cross-activation of the insulin-like growth factor 1 receptor (IGF1R) family, resulting in activation of downstream signaling cascades." (PMID 28038446, 2017). "While the mRNA expression levels of GHR, IGF1 and IGF1R were increased in non-tumor tissues, they were downregulated in the tumors." (PMID 28710407, 2017). "IGF-1R also mediates anchorage-independent growth and survival, and migration, thus facilitating tumor establishment and progression." (PMID 29387053, 2017). "On the other hand, E0771 cells responded to IGF-1 stimulation and expressed much higher level of IGF-1R than B16F1 cells, suggesting that HSC-Ad rely more on the IGF-1/IGF-1R signaling pathway to regulate E0771 tumor growth." (PMID 28989976, 2017). "The present work also elucidates a major molecular pathway that underlies IMP2’s tumor promoting activity; IMP2 occupies a central place in a network of gene products that drive proliferation through the IGF1R and INSR-A." (PMID 28753127, 2017). "Positive IGF-1 and IGF-1R immunoreactivities were seen also in the tumor micro-environment, including cells lining the bone surfaces, likely osteoblasts." (PMID 28447314, 2017). "By targeting both IGF1R and mTOR, miR-497 or miR-99a exerted remarkable tumor suppressive function in vivo and in vitro." (PMID 28624790, 2017). "Quantitative evaluation of IGF-1/IGF-1R expression combined with molecular assessment of T2E status or ERG protein expression represents a useful marker for tumor progression in localized PCa." (PMID 28545426, 2017). "NGS transcriptome analysis did shed light on the specific tumor development and progression in relation to chronic IGF1R activation." (PMID 28173837, 2017). "At 25 days, the tumor volume and weight were markedly decreased in miR-99a or miR-497 over-expressed tumors compared to the control as IGF1R and mTOR were down-regulated in the xenograft tumors." (PMID 28624790, 2017). "Our findings establish that Klotho performs as a tumor suppressor and modulator of IGF-1R signaling in DLBCL." (PMID 28153033, 2017). "miR-223 has been found to affect the cell cycle by regulating E2F1 35, migration and invasion in cancer cells by targeting EPB41L3 36, proliferation and tumor growth of cells by targeting IGF1R and downstream Akt/mTOR/p70S6K signaling pathway 37,38." (PMID 29090068, 2017). "In tumor lesions, the local expression of CCL5 was negatively associated with the expression of IGF1R." (PMID 29156819, 2017). "Taken together, our findings identified that Klotho performs as tumor suppressor and modulator of IGF-1R signaling in the DLBCL." (PMID 28153033, 2017).
tumor (continued). "Functional assay revealed that ectopic expression of miR-497 or miR-99a in HCC cells resulted in a significant inhibition on tumor growth and invasiveness in vitro and tumor development in vivo via repressing the expression of IGF1R and mTOR." (PMID 28624790, 2017). "These synergistic anti-tumor effects further support a role for IGF-1R as a mediator of resistance to anti-EGFR agents." (PMID 28002810, 2017). "Of note, the cell surface HS proteoglycan syndecan-1 coupled ternary receptor complex (prevalent on tumor cells and activated endothelial cells) has been described, whereby syndecan-1 clusters IGF-1R and integrins, leading to integrin activation." (PMID 28038446, 2017). "Patients with tumors with both pIGF1R/InsRpos and IGF1Rstrong expression had a worse prognosis only when the tumor also expressed mod/strong levels of InsR, suggesting formation of IGF1R/InsR heterodimers." (PMID 28030849, 2017). "More importantly, we also found that this particular tumor had significantly increased expression of total IGF1R, p-IGF1R, total p65 and p-p65." (PMID 29190911, 2017). "IGF1R activation seems to play an essential role in cancer cell proliferation of different tumor cell entities including BON-1 cells." (PMID 28800359, 2017). "Overall, our results suggest that miR-497 and miR-99a both function as tumor-suppressive miRNAs by suppressing IGF1R/mTOR signaling pathway." (PMID 28624790, 2017). "This justifies further examination of a possible connection between tumor cell expression of IGF-1R and tumor cell immune-evasion." (PMID 28447314, 2017). "The interaction between miRNA-497 and IGF1R/mTOR were further collaborated by the inversely correlated expressions of miR-497 and IGF1R/mTOR in HCC tumor tissue and cell lines." (PMID 28624790, 2017). "Numerous studies have pointed at the importance of IGF-1 and its receptor (IGF-1R) during the process of malignant transformation and for stimulation of tumor growth." (PMID 28447314, 2017). "Such inhibition on the tumor growth was synergistically strengthened in miR-497 and miR-99a co-expressing group via synergistically suppressing IGF1R and mTOR, which is consistent with the observation in the in vitro assay." (PMID 28624790, 2017). "The tumor sample of patient #4 in the discovery set had both MRAS mutation and IGF1R amplification, but the tumor sample of patient #17 with IGF1R amplification in the validation set did not have MRAS mutation." (PMID 27891760, 2017). "Two of these drugs, Cixutumumab and Bevacizumab, each target a single gene that controls important biological processes for tumor progression: cellular proliferation by inhibiting IGF1R and vascularization by inhibiting VEGFA, respectively." (PMID 29152063, 2017). "Our findings, as presented here, indicate a benefit in TNBC outcomes by inhibiting IGF2 activity using targeted therapies against IGF1R/IR and AR to prevent tumor growth and potentially metastasis." (PMID 29099049, 2017). "Nuclear localization of IGF‐1R is emerging as a potentially important factor in tumor pathophysiology and clinical prediction." (PMID 28112398, 2017). "A number of other tyrosine kinase proteins commonly associated with cancer, such as IGF-1R, c-Met and Src, have been shown to co-operate with HER-family members to drive tumour growth and confer resistance to treatments." (PMID 28638122, 2017). "It has been demonstrated that miR-375 negatively regulates PDK1 and IGF1R and that these effects contribute to the inhibition of tumor proliferation and metastasis." (PMID 27885434, 2017). "Tumor cell IGF-1R immunoreactivity was evaluated in clinical PCa bone metastases (n = 61), and positive staining was observed in most cases (74%)." (PMID 28447314, 2017). "Other microRNAs that affect HBV replication indirectly through regulation of host proteins include miR-99a, which acts as a tumor suppressor that targets insulin-like growth factor 1 receptor (IGF-1R) and induces cell cycle arrest." (PMID 26927063, 2016).
tumor (continued). "Recently, we found that NNK stimulates IGF-1R activation in lung epithelial cells, promoting tumor formation (manuscript submitted for publication)." (PMID 27708216, 2016). "The over-expression of IGF1R, which mediates tumor growth, adhesion, and protection from apoptosis, has been observed in various cancers." (PMID 27835574, 2016). "The high expression of IGF2 was maintained in the metastasis; moreover the expression of its receptor IGF1R was slightly upregulated in the primary tumor and the metastasis." (PMID 27825128, 2016). "We then assessed the anti-proliferation effects of metformin on a panel of NSCLC cell lines, and our results suggested that the anti-tumor effect of metformin was at least partially though the inhibition of IGF-1R signaling pathway." (PMID 27488947, 2016). "Microarray-based mRNA expression levels confirmed higher expression of IRS1, IGF2, IGF1R and AR in “NFκB off” compared to the “NFκB on” tumours in all five datasets." (PMID 26943587, 2016). "Together, these results show that AE modulates cancer cells and the tumor microenvironment via activation of miR-375 and by targeting IGF1R and SNAIL1 in OC cells." (PMID 27129171, 2016). "Complexes of uPAR and uPA significantly correlated with IGF1R (p = 0.0032), cathepsin B and D (p ≤ 0.0001, respectively) expression and inversely with the tumour size (p = 0.0065)." (PMID 27502396, 2016). "A comparison to already existing IGF-1R Mabs with respect to anti-tumor activity and toxicity should also be made." (PMID 27384680, 2016). "In vivo effects of AE on tumor growth and on miR-375 target IGF1R (promotes proliferation and growth), SNAIL1 (promotes EMT) and E-cadherin (opposes EMT) were assessed to confirm in vitro findings." (PMID 27129171, 2016). "In particular, this drug interferes with the insulin/IGF-1R system in tumor cells as shown in pancreatic, breast, endometrial, prostate and lung cancers." (PMID 27391065, 2016). "IGF-1R was detected in the plasma membrane and cytoplasm and was expressed more strongly in recurrent tumor than the primary." (PMID 27200287, 2016). "Other tumor suppressor gene VHL, Von Hippel–Lindau tumor suppressor also inhibits IGF1R promoter activity through interaction with Sp1 protein." (PMID 27405474, 2016). "The amounts of IGF-1R were greater in tumor biopsies taken at the time of acquired resistance when compared to those obtained from the respective pre-resistant tumors." (PMID 27144340, 2016). "Mice with BxPC-3 tumors, orthotopically-implanted in the tail of the pancreas were injected with a single 10 μg dose of DyLight 650-conjugated anti-IGF-1R (clone 24-31) in 150 μl PBS dose via the tail vein 14 days after tumor implantation." (PMID 26919100, 2016). "Here, we present in vitro data showing that tetraspecific antibodies-targeting HER1, HER3, IGF1R and cMet can be superior to BsAbs with respect to apoptosis induction and tumor growth inhibition." (PMID 27578890, 2016). "Overexpression of IGF2 is seen in at least 95% of ACC tumor samples studied, prompting clinical trials employing Insulin-Like Growth Factor 1 Receptor (IGF1R) inhibitors." (PMID 26963385, 2016). "It has been shown that R1507, a monoclonal antibody targeting the human IGF-1R, results in the inhibition of the proliferation of several cancers, such as lung, breast, prostate cancers, and postpones the growth of xenograft tumor in nude mice." (PMID 27813495, 2016). "Concordantly, TUNEL and caspase 3/7 profiling revealed activated PSCs protect tumor cells from apoptosis and sensitize tumor cells to reciprocal node inhibitors (IGF1R/AXL and AKT)." (PMID 27087446, 2016). "Clinicopathological data showed that high IGF-1R mRNA expression was more frequent in HCC patients with poor tumour differentiation and with TEPV." (PMID 27813495, 2016). "We found in both cells and tumors a marked upregulation in CTFG and a significant reduction of SLP1 expression in the CD24+/IGF1R-KD; tumor-suppressor and tumor-promoting genes respectively." (PMID 27179633, 2016).
tumor (continued). "Measurement of tumor volume showed that Huh7 cells stably expressing IGF-1R siRNA formed significantly smaller tumors than Huh7 cells stably expressing negative control, or untreated Huh7 cells (blank control)." (PMID 27813495, 2016). "Insulin-like growth factor 1 receptor (IGF1R) is an important molecule involving the tumor immunity." (PMID 27463019, 2016). "In other words, our model proposes that the IGF1R gene constitutes a common downstream target for multiple tumor suppressors." (PMID 27446805, 2016). "The IGF-1R/InsR signaling as an anti-tumor target has accordingly been studied in preclinical NSCLC models using either small molecule inhibitors towards the kinase domain or IGF-1R/InsR targeting antibodies." (PMID 27384680, 2016). "Direct tumour-promoting interactions of uPAR with uPA and the insulin-like growth factor receptor 1 (IGF1R) were shown in TNBC cells and these interactions were significantly reduced (p = 0.001) when uPAR was downregulated." (PMID 27502396, 2016). "SNPs of the IGF1R (rs12423791), and IGF1 (rs2162679, rs5742612, rs35767) genes were significantly associated with tumor response to FOLFOX." (PMID 27144430, 2016). "Reciprocal colony growth is dependent on SHH activation of PSCs and IGF1R/AXL-AKT activity in tumor cells." (PMID 27087446, 2016). "Analysis of tumor tissue lysates by phospho-RTK array showed a prominent tyrosine phosphorylation of EGFR, ERBB4, INSR and IGF1R in control which was remarkably decreased in tumor from treated mice." (PMID 27374103, 2016). "In all tumor samples, there was detectable membrane and cytoplasmic IGF-1R, with clearly apparent nuclear positivity that showed heterogeneity between different regions of tumor, and was most evident in the 2008 (pre-trial) recurrence." (PMID 27200287, 2016). "Transgenic overexpression of IGF1R increases epithelial mammary gland hyperplasia and tumor formation." (PMID 27405474, 2016). "Fluorescently-conjugated anti-IGF-1R antibodies made the tumor more fluorescent than background, easily distinguishing tumor from surrounding normal organs." (PMID 26731105, 2016). "Several SNPs of the IGF1R (rs12423791), and IGF1 (rs2162679, rs5742612, rs35767) genes were significantly associated with tumor response." (PMID 27144430, 2016). "In vitro studies showed high expression of insulin growth factor receptor IGF-1R and loss of function of PTEN in SS18-SSX -positive tumours." (PMID 27266712, 2016). "Mice with tumors orthotopically-implanted in the mouse cecum were injected with DyLight 650-conjugated anti-IGF-1R (clone 24–31) antibody with a single 30 μg dose via the tail vein 14 days after tumor implantation." (PMID 26731105, 2016). "By employing Ingenuity pathway analyses on the altered genes, decreased IGF-1R signaling in response to treatment of tumor cells with compound 2 was evident." (PMID 27384680, 2016). "Ganitumab inhibits the IGF signaling pathway by binding to IGF1R and thus inhibits proliferation of tumor cells." (PMID 27806321, 2016). "IGF1-R overexpression increases tumor progression, and decreases of IGF-1R expression or activity causes tumor growth arrest and apoptosis." (PMID 27323414, 2016). "Of note, one sample also showed IGF1R expression present in a matched set of primary tumor, secondary tumor and microscopically-uninvolved meninges." (PMID 27255663, 2016). "Consistent with the previous studies, we also demonstrated that, using CRC cell line and xenograft tumor cells, IGF1R positively mediated sphere-forming capacity, tumor-initiating/propagating capacity of CEA−/lo cells but not CEA+ cells." (PMID 27813496, 2016). "IGF/ IGF1R signaling stimulates tumor progression in some types of cancer, suggesting that this system is an attractive therapeutic target." (PMID 27487118, 2016). "In view of this, a better understanding of the limited role of IGF1 or IGF1R in regulating tumor progression will potentially re‐evaluate their functions." (PMID 26923183, 2016).